CTLA4 (cytotoxic T-lymphocyte associated protein 4)
Diseases named in the same sentence as CTLA4 in open-access papers (continued):
Sharing a sentence is not in itself a finding about the gene and the disease.
breast carcinoma (429 papers, 2007 to 2026). "The correlation of the CC genotype with chronic HCV infection and hepatocarcinogenesis in our study aligns with prior studies, where increased CTLA-4 expression is associated with impaired immune responses to breast cancer." (PMID 41303553, 2025). "One of the most significant challenges in breast cancer treatment is the limited efficacy of ICIs, such as anti-PD-1 and anti-cytotoxic T-lymphocyte-associated protein 4 (CTLA-4) therapies." (PMID 40486614, 2025). "Our findings showed that miR-26a-5p is downregulated in breast cancer and is associated with immune suppression through pathways like NF-κB signaling and CTLA4 inhibition." (PMID 40861477, 2025). "High levels of CTLA-4 expression, exceeding the 63rd percentile, are linked to very low rates of recurrence and breast cancer-related deaths in the Oslo1, SCAN-B, and METABRIC groups." (PMID 41550427, 2025). "High CTLA-4 expression in breast cancer patients is linked to increased lymph node metastasis and lower survival rates, potentially serving as an indicator for immunotherapy." (PMID 39741315, 2024). "CTLA-4 polymorphism contributes to the development of autoimmune diseases and malignancies, such as renal and breast cancers." (PMID 38046481, 2023). "Overexpression of CTLA-4 protein in four different breast cancer and tumorigenic cell lines indicates its association with resistance towards radiotherapy." (PMID 36813833, 2023). "The antibodies of programmed cell death receptor 1 (PD-1), programmed cell death 1 ligand 1 (PD-L1), and cytotoxic T-lymphocyte-associated antigen-4 (CTLA-4) have been applied as ICIs for the treatment of breast cancer." (PMID 37828454, 2023). "It was observed that the polymorphisms of the CTLA-4 gene are associated with breast cancer in the populations of Iran." (PMID 38186404, 2023). "Earlier studies have reported that the polymorphisms of the CTLA-4 gene are associated with diseases of autoimmunity like hepatic cancer, Graves’ disease, kidney disease, breast cancer, vitiligo, systemic lupus erythematosus, and type I diabetes." (PMID 38186404, 2023). "Substantial progress has been made in clinical studies employing cytotoxic T lymphocyte-associated antigen-4 (CTLA-4) inhibitors for breast cancer, but the cure rates are relatively low." (PMID 37860188, 2023). "sought to determine an optimal radiation dose that maximized production of IFN-1 while minimizing TREX1 expression using a mammary carcinoma mouse model treated with RT and an antibody against anti-cytotoxic T-lymphocyte-associated protein 4 (CTLA-4)." (PMID 36387120, 2022). "Currently, the most clinically relevant immune checkpoints (ICPs) include CTLA-4 (cytotoxic T-lymphocyte-associated protein 4) and, in breast cancer, the PD-1 (programmed cell-death protein 1)/PD-L1 (programmed death-ligand 1) axis." (PMID 36289918, 2022). "For example, the high expression of CTLA4 showed a poor survival and serves as an independent risk factor to evaluate the prognosis of breast cancer." (PMID 35675043, 2022). "TMCs 4-8 were associated with PD-1/PD-L1/CTLA4 expression in diverse cancer types, such as breast cancer and skin melanoma." (PMID 34899684, 2021). "Breast cancer associated TREG cells show a significantly higher expression of CTLA-4 and tumor necrosis factor receptor superfamily, member 4 (TNFRSF-4, also known as OX-40) on their membranes compared to other CD4+ and CD8+ T cells." (PMID 33467084, 2021). "In meta-analysis studies, CTLA-4 polymorphisms have been shown to correlate with breast cancer susceptibility, emphasizing the importance of CTLA-4 in regard to tumor development." (PMID 34440813, 2021). "Several studies have however associated poorer clinical outcomes of breast cancer patients with the expression of CTLA-4 in the tumor microenvironment, justifying the enormous need for further research in this field." (PMID 34440813, 2021).
breast carcinoma (continued). "Co-culture of PBMC with MCF-7 breast cancer cells is causing an increase in CTLA-4 and PD-1 expression within lymphocytes." (PMID 34440813, 2021). "Tan IIA was shown to inhibit breast cancer BT-20 cells by inhibiting the expression of PD-L1, cytotoxic T-lymphocyte-associated antigen 4 (CTLA-4), cluster of differentiation 80 [B7-1 (CD80)], and B7-2 (CD86)." (PMID 32265690, 2020). "Accordingly, a previous study also reported elevated serum CTLA-4 levels in cats with mammary carcinoma, being associated with HER2-positive status and TNF-α levels, in accordance with our findings." (PMID 32481540, 2020). "On the other hand, a high CTLA4 mRNA level was associated with breast cancer patients having higher clinical staging and lymph node metastasis." (PMID 33014010, 2020). "It has been examined that expression of CTLA-4 is associated with age, with increased expression in elderly breast cancer." (PMID 33033520, 2020). "CTLA‐4 is also expressed on multiple tumor cell types, and breast cancer cell‐associated CTLA‐4 was found to suppress DC maturation, most likely through its ability to promote ERK and STAT3 signaling in these cells." (PMID 32508018, 2020). "Cytotoxic T lymphocyte associated antigen 4 (CTLA-4) serves an important role in breast cancer progression, which has led to the development of novel immunotherapies aimed at blocking tumor immune evasion." (PMID 32123292, 2020). "rAd.sT enhanced the efficacy of concomitant anti-PD-1 and anti-cytotoxic T-lymphocyte-associated protein 4 (CTLA-4) treatment in an immunocompetent 4T1 breast cancer model." (PMID 33202717, 2020). "CTLA-4 expression was associated also with breast cancer stage and was confirmed by protein expression in cervical cancer." (PMID 29785404, 2018). "High levels of CTLA-4 mRNA in primary breast cancers were shown to be associated with ALN metastases and advanced tumours." (PMID 29390966, 2018). "In other in vivo studies, Tregs were suppressed by blockage of cytotoxic T-lymphocyte associated protein 4 (CTLA4) in mice injected with 4T1 mouse mammary carcinoma or CD-26 murine colon cancer cells." (PMID 28638385, 2017). "By contrast, in 60 breast cancer patients, higher levels of tumoral CTLA4 were associated with advanced clinical stage." (PMID 28038471, 2017). "In summary, our meta-analysis suggests that rs231775, rs3087243 and rs4553808 polymorphisms in human CTLA-4 gene significantly associated with breast cancer susceptibility in Asians, particularly in the Chinese population." (PMID 28097051, 2017). "This suggested that CTLA-4 −1661G allele is more likely to be a risk factor of breast cancer than A allele." (PMID 28097051, 2017). "The results indicated that the CTLA-4 +49A>G (rs231775) polymorphism had a significant association with decreased breast cancer risk in allelic, homozygous, dominant and recessive models." (PMID 28097051, 2017). "Previous studies have investigated the association between cytotoxic T-lymphocyte antigen-4 (CTLA-4) polymorphisms and breast cancer susceptibility, but the results remained inconsistent." (PMID 28097051, 2017). "Subsequent study demonstrated that the activation of extracellular-signal regulated kinase and signal transducer and activator of transcription 3 of DCs caused by CTLA-4+ breast cancer cells were the predominant mechanism of DC suppression." (PMID 28099147, 2017). "In breast cancer cases, CTLA-4 expression was associated with axillary lymph-node metastases and higher tumor stages." (PMID 27741514, 2016). "Previous studies implicated CTLA-4 in immune dysregulation of breast cancer and found CTLA-4 to be highly expressed in breast tumor cells." (PMID 25893809, 2015). "CTLA-4 1661 G and 318 T allele carrier’s frequencies were significantly higher in breast cancer patients than in the control group." (PMID 25013611, 2011).
breast carcinoma (continued). "Reports indicate that breast cancer susceptibility and prediction can be influenced by the polymorphism of cytotoxic T-lymphocyte antigen-4 (CTLA-4) gene, which encodes a classic molecule offering a co-inhibitory signal to T cell activation." (PMID 19903360, 2009). "In the case-control study described here, we investigated the association between five putatively functional polymorphisms (-1661 G/A, -658 T/C, -318 T/C, +49 G/A and CT60 G/A) of the CTLA-4 gene and the risk of sporadic breast cancer in Chinese Han women." (PMID 17825114, 2007). "Polymorphisms in the CTLA-4 gene have been tested for association with breast cancer in an Iranian population." (PMID 17825114, 2007). "Consequently, immunotherapy for breast cancer has specifically targeted the immune checkpoint proteins PD-1 and cytotoxic T-lymphocyte associated antigen 4 (CTLA-4)." (PMID 39507526, 2024). "To investigate whether TN-BCSCs can participate in tumor immune escape via CTLA4, we obtained the breast cancer-associated single-cell RNA sequencing (scRNA-seq) dataset GSE180286 from Gene Expression Omnibus (GEO)." (PMID 37838657, 2023). "Accordingly, CTLA-4 overexpression was associated with poor survival in breast cancer patients." (PMID 36813833, 2023). "It was reported for the first time that the CTLA-4 genotype located in the promoter −658 CC may increase breast cancer risks; however, the allele −658T has shown protective effects in breast cancers." (PMID 38186404, 2023). "Combined anti-PD-1 and anti-CTLA-4 ICIs with palliative radiotherapy was found to be associated with few adverse events in patients with non-small cell lung cancer, melanoma, renal cell cancer, and breast cancer." (PMID 36387071, 2022). "In addition, the m6A regulator-related risk scores were previously found to be correlated with CTLA4 and PD-L1 in breast cancer." (PMID 35260168, 2022). "A stratified cancer type analysis showed that CTLA-4 rs231775 polymorphism was a risk factor for colorectal cancer and thyroid cancer; on the other hand, it was a protective factor for breast cancer, liver cancer, cervical cancer, bone cancer, head and neck, and pancreatic cancer." (PMID 35600409, 2022). "The main immune checkpoints for breast cancer include cytotoxic T-lymphocyte-associated protein-4 (CTLA-4), programmed death receptor 1/programmed cell death ligand 1 (PD-1/L1), lymphocyte activation gene 3 (LAG-3), T cell immunoglobulin domain and mucin 3 (TIM-3) and other molecules." (PMID 34631507, 2021). "The signal peptide missense variant in cancer-brake gene CTLA4 was associated with lower risk and poor prognosis in breast carcinoma among Egyptian women, might have prognostic as well diagnostic impact in breast cancer." (PMID 33980272, 2021). "Moreover, high CTLA-4 expression was associated with short OS and disease-free survival of breast cancer cases and NSCLC due to downregulation of effector T-cell function and upregulation of regulatory immunosuppressive T-cell." (PMID 35047074, 2021). "A recent study found that high CTLA4 expression is associated with poor prognosis in breast cancer." (PMID 34729098, 2021). "Moreover, developing strategies on combining different ICBs are appealing in breast cancer treatment, such as combining anti-PD-1/PD-L1 with anti-cytotoxic T-lymphocyte associated protein-4 (anti-CTLA-4) or other co-inhibitory molecules." (PMID 32258038, 2020). "In conclusion, the present study demonstrated a positive association between serum CTLA-4 levels and two pro-inflammatory cytokine serum levels in cats with mammary carcinoma, with higher serum CTLA-4 levels being associated with less aggressive clinicopathological features." (PMID 32123292, 2020).
breast carcinoma (continued). "A promising immunotherapy in breast cancer is the newly developed antibodies to programmed cell death ligand-1 (PD-L1) and cytotoxic T-lymphocytic associated protein 4 (CTLA-4) that interferes with robust immune surveillance and escape by exhausting T cells in the tumor microenvironment." (PMID 33324554, 2020). "Previous studies have demonstrated that breast cancer patients showed an increased spontaneous expression of cytotoxic T-lymphocyte–associated antigen 4 (CTLA-4) on T lymphocytes in breast tissue and peripheral blood mononuclear cells, leading to impaired T cell activation." (PMID 31536611, 2019). "We found that breast cancer cells upregulate the expression of ICs including PD-1, cytotoxic T lymphocyte-associated antigen-4 (CTLA-4), T cell immunoglobulin and mucin domain-containing protein 3 (TIM-3) and lymphocyte activation gene-3 (LAG-3) in CD4+ T cell subsets." (PMID 31614877, 2019). "LY6E, together with LY6K, has also been implicated in breast cancer proliferation by altering TGFβ-dependent breast cancer cell physiology, resulting in increased immune checkpoint molecules PD-L1 and CTLA4 in tumor-infiltrating T regulatory cells yet decreased natural killer (NK) cell activation." (PMID 31684192, 2019). "Moreover in human breast cancer, high tumor CTLA-4 expression is associated with shorted OS, disease-free survival and worse prognosis." (PMID 29682176, 2018). "In conclusion, CTLA-4 polymorphisms significantly associate with breast cancer susceptibility in Asian populations, and different gene loci may have different effects on breast cancer development." (PMID 28097051, 2017). "Therefore, we evaluated the relationship between four common CTLA-4 polymorphisms and breast cancer risk by a meta-analysis, aiming to derive a comprehensive and precise conclusion." (PMID 28097051, 2017). "Numerous investigations have demonstrated that CTLA-4 genetic polymorphisms may have association with human breast cancer susceptibility." (PMID 28097051, 2017). "Our meta-analysis suggests that the CTLA-4 -1661A/G polymorphism is a potential factor for the susceptibility of cancer, especially in gastric cancer, breast cancer and other cancers, and the CTLA-4 60G/A polymorphism is significantly associated with increased skin cancer risk." (PMID 24376736, 2013). "In the present study, our meta-analysis suggests that the CTLA-4 -1661A/G polymorphism is a potential factor for the susceptibility of cancer, especially in gastric cancer, breast cancer and other cancers, and the CTLA-4 60G/A polymorphism is significantly associated with increased skin cancer risk." (PMID 24376736, 2013). "This was the first study indicating that in the CTLA-4 promoter -658 CC genotype may increase breast cancer risk and -658T allele has a protective role in breast cancer." (PMID 17825114, 2007). "Our data suggest that the CTLA-4 gene may be involved in the susceptibility to and progression of breast cancer in the Chinese Han population." (PMID 17825114, 2007). "To evaluate whether these polymorphisms of the CTLA-4 gene were likely to be of importance in Chinese breast cancer, we typed patients and controls for five of these important SNPs in the Chinese Han population of Northeast China." (PMID 17825114, 2007). "Recent research suggests the CTLA-4 gene SNPs -318C/T could affect gene expression and alter the susceptibility to many kinds of cancer, such as cervical cancer, lymphoma, leukemia, and breast cancer." (PMID 38046481, 2023). "In breast cancer patients, several immune checkpoints, including programmed cell death protein 1 (PD-1) and cytotoxic T-lymphocyte-associated protein 4 (CTLA-4), seem to be related to the specific tumour subtype, but the relationship between expression and prognosis remains unclear." (PMID 36982588, 2023).
breast carcinoma (continued). "In this breast cancer-focused review, we explore the interactions between autophagy and two clinically relevant immune checkpoint pathways; the programmed cell death-1 receptor with its ligand (PD-L1)/PD-1 and the cytotoxic T-lymphocyte-associated protein 4 (CTLA-4)/CD80 and CD86 (B7-1 and B7-2)." (PMID 36295867, 2022). "In our study, it was shown that the low-risk patients had significantly higher levels of PD-1, PD-L1, PD-L2, CD80, CD86, and CTLA-4 than the high-risk patients, suggesting this low-risk subpopulation of breast cancer patients might benefit more from immune checkpoint blockade therapy." (PMID 36936274, 2022). "Recent research from clinical trials has demonstrated that a single dose of anti-CTLA-4 monoclonal antibody (ipilimumab) leads to increased intratumor T cell density, which is associated with a lower risk of chemotherapy resistance and higher overall survival in breast cancer patients." (PMID 34440813, 2021). "Additionally, earlier studies utilizing murine models of breast cancer demonstrated that local radiotherapy effectively inhibited growth of the induced primary tumors, especially when the irradiations were associated with blockade of the function of CTLA-4." (PMID 34208396, 2021). "Although the −1661 is less characterized than other SNPs in the CTLA-4 gene, it has been associated with increased risk of multiple sclerosis, type 1 diabetes mellitus systemic sclerosis, oral squamous cell carcinoma, and lymph node involvement in breast cancer." (PMID 27118383, 2016). "Blockade of one of these checkpoints, cytotoxic T-lymphocyte-associated antigen 4 (CTLA-4) or the programmed death 1 (PD-1) receptor may provide proof of concepts for the activity of an immune-modulation approach in the treatment of a breast cancer." (PMID 25932042, 2015). "Thus, CTLA-4high expression in breast cancer cells might indicate an immunosuppressive tumor microenvironment, which could explain the association between higher CTLA-4 expression in breast cancer cells and poor prognosis, as demonstrated by this study." (PMID 25893809, 2015). "A positive influence of interstitial lymphocytes with high CTLA-4 on outcome has also been reported in breast cancer patients." (PMID 39751903, 2025). "In syngeneic mouse models of mammary carcinoma and mesothelioma, significant immune-related antitumor activity of DNA methyltransferase inhibitors was shown when combined with CTLA-4 blockade." (PMID 40805133, 2025). "For example, combination treatment of a MMPI and anti-CTLA-4 antibody has been shown to inhibit tumor growth and metastases in breast cancer model in mice." (PMID 40611940, 2025). "88% of cell lines have CTLA-4 expression at different densities, according to flow cytometry studies, with osteosarcoma and breast cancer cell lines exhibiting the strongest staining." (PMID 39905036, 2025). "Breast cancer cells utilize CTLA-4 to physically remove CD80/CD86 from antigen-presenting cells via force-mediated trans-endocytosis." (PMID 41550427, 2025). "In breast cancer models, eosinophils mediated the anti-tumor effects of CTLA4 blockade through vascular remodeling." (PMID 40050933, 2025). "A correlation between CTLA4 expression and treatment outcomes in breast cancer has been described previously, but a subgroup with excellent prognosis has not been identified." (PMID 40523912, 2025). "In order to define a suitable cutoff value for CTLA4 expression, we performed a ROC analysis with breast cancer-related death as the dependent variable and CTLA4 expression as the independent variable." (PMID 40523912, 2025). "Setting the relative cost to 3 resulted in a cutoff corresponding to the 63rd percentile of CTLA4 expression, with a sensitivity of 100% and a specificity of 51.5% for breast cancer-specific death." (PMID 40523912, 2025).